STAT3 (signal transducer and activator of transcription 3)
Diseases named in the same sentence as STAT3 in open-access papers (continued):
Sharing a sentence is not in itself a finding about the gene and the disease.
tumor (continued). "Studies showed that STAT3 is preferentially activated in human HCC and active STAT3 is linked with aggressive tumor phenotype." (PMID 31450841, 2019). "Level of active STAT3 (pSTAT3) was measured by immunoblotting of total proteins isolated from different cytopathological grades of tumor tissues." (PMID 31487312, 2019). "STAT3 phosphorylation is considered to be driven by inflammatory and immunosuppressive cytokines and growth factors produced by both tumor and tumor-infiltrating cells including IL-6, IL-10, or VEGF-A." (PMID 31781102, 2019). "In a cohort of 169 patient-derived tumor samples from cases of peripheral T cell lymphoma (PTCL), immunohistochemistry on tumor tissue microarrays demonstrated positive phospho-(p)STAT3 staining in 38% of samples." (PMID 31684088, 2019). "In our experimental system, STAT3 is the main signal transducer leading to endothelial induced tumour cell migration, as inhibition with the STAT3 signalling inhibitor FLLL31 is sufficient to repress endothelial cell-dependent migration of SK-BR-3 cells." (PMID 30947697, 2019). "Recent studies suggest that STAT3 exhibits either pro-oncogenic or tumor-suppressive activity depending on the tumor aetiology/mutational landscape." (PMID 31296870, 2019). "Accordingly, by using double sequential immunostaining, a significant fraction of STAT3+ tumor cells in a set of basal-type MIBC co-expressed MYC and FOSL1." (PMID 31438567, 2019). "An increase in lipid oxidation enhanced the immunosuppressive properties of MDSCs through the activation of STAT3 signaling in the tumor microenvironment." (PMID 31129755, 2019). "Increasing evidence has revealed that IL-6 promotes tumour development through the STAT3 signalling pathway." (PMID 31324197, 2019). "We showed that NEAT1 functions as an oncogenic sponge for the tumor suppressor microRNA-361 (miR-361), which suppresses proliferation, invasion, sphere formation and TX resistance by directly targeting the oncogene STAT3." (PMID 31287002, 2019). "A number of studies have highlighted the role of IL-6 and STAT3 in promoting tumor metastasis as their overexpression and/or hyper-activation have been reported in several human cancers." (PMID 30744595, 2019). "Histologically, combined treatment with PPP and low dose of ASP3026 was associated with expanded areas of tumor cell necrosis, decreased proliferation index as evaluated by Ki-67 staining, and downregulation of phosphorylated IGF-IR and STAT3." (PMID 31340850, 2019). "Together, our data indicate that PH inhibited the tumor growth both in vitro and in vivo through a STAT3 inhibition mechanism involving SHP-1." (PMID 31619257, 2019). "Aberrant functioning of Notch-1, Wnt/β-catenin, and STAT3 proteins and their crosstalk signaling pathways have been found to be involved in tumor survival, drug resistance, and relapse." (PMID 31357721, 2019). "Pre-treating human PCSCs with increasing concentrations of a STAT3 inhibitor abrogated in vivo tumor-propagating ability." (PMID 31878027, 2019). "Loading a combination of ELTN and FDTN on NPs not only enhances the anti-tumor activity by inhibition of the JAK2/STAT3 signaling pathway, but also diminishes the systemic adverse effects." (PMID 31569687, 2019). "Tumor-derived factors propagate persistent activation of STAT-3 in immune cells; this is manifested in immature phenotype and immunosuppressive characteristics of DC and monocytes." (PMID 31555270, 2019). "Signal transducer and activator of transcription 3 (STAT3) plays a critical role in promoting the proliferation and survival of tumor cells." (PMID 31671769, 2019).
tumor (continued). "They would limit toxicity by using tumor-associated receptors to target IFNs to the TME and suppress STAT3 activation, while simultaneously, activating STAT1/2 in both tumor cells and immune cells." (PMID 31684144, 2019). "By virtue of its ability to upregulate MMP-9, STAT3 appears to robustly enhance tumor migration and invasion of MDA-MB-231 cells." (PMID 31456939, 2019). "The phosphorylation of p38 and STAT3 was also decreased in tumor tissues of ApoE KO mice compared to those of WT mice." (PMID 31275318, 2019). "STAT5 is an example of this case and it is capable of regulating the expression of STAT3 in tumor cells." (PMID 31569687, 2019). "Together, our results demonstrate that ACVR1 R206H and H3.1K27M promote tumor initiation, accelerate gliomagenesis, promote a mesenchymal profile partly due to Stat3 activation, and identify LDN212854 as a promising compound to treat DIPG." (PMID 30833574, 2019). "We analyzed the expression of Cyclin D1 and Survivin, which are involved in tumor proliferation and are downstream molecules of STAT3 signaling." (PMID 30832202, 2019). "An interesting mechanism for the tumor suppressor role of STAT3 was recently described in the prostate where STAT3 induces the expression of p19ARF." (PMID 31557897, 2019). "Cytokines whose expression is induced in response to NF-kB in immune cells of the tumor microenvironment lead to STAT3 activation in both malignant and immune cells." (PMID 31205871, 2019). "Western blotting confirmed that the PIK3R1-shRNA tumor nodules maintained decreased levels of p85α and increased levels of STAT3 and AKT phosphorylation." (PMID 30755611, 2019). "Inhibition of tumor growth, downregulation of p-STAT3/5 expression levels, downregulation of Ki-67 expression (as a marker for inhibiting cell proliferation), inhibit angiogenesis." (PMID 31402861, 2019). "Second, we showed that metformin and resveratrol, two SIRT1 activators, entail STAT3 acetylation leading to Th17 differentiation impairment and limit tumor growth in mice." (PMID 31480382, 2019). "These evidences suggest that dynasore exerts anti-tumor effect, or at least anti-proliferation effect, in OS via STAT3 signaling pathway." (PMID 31534119, 2019). "For this, the tumor tissues were treated with vehicle and 50 mg/kg body weight of zerumbone for 6-week duration and substantial inhibition of STAT3 activation was noted." (PMID 30781671, 2019). "Research in past decades has facilitated our comprehension of the critical roles of aberrant STAT3/STAT5 activation in EOC cells as well as in the tumor microenvironment." (PMID 31861720, 2019). "The activation of the IL-6/STAT-3 signaling axis apparently is an important event in cancer because it promotes carcinogenesis by regulating multiple survival signaling pathways in tumor cells." (PMID 31602271, 2019). "Human prostaspheres display elevated levels of STAT3 activation and STAT3 knockdown leads to reduced sphere formation and in vivo tumor growth." (PMID 31878027, 2019). "Our findings demonstrated that NPM-ALK/STAT3-driven miR-135b potentiates tumor progression via multiple targets—including FOXO1, STAT6, GATA3, and PPP2R5C—in ALK-positive ALCL." (PMID 31878193, 2019). "The results revealed significant upregulation of the expression of STAT3 and mTOR in the tumor tissues compared with the corresponding normal tissue." (PMID 31287013, 2019). "The IL-6/STAT3 pathway regulates a number of gene expressions such as Bcl-2 that mediate proliferation or inhibit apoptosis during tumor formation." (PMID 31361777, 2019). "The high expression of p-STAT3 in malignant tumor cells and the expression level of p-STAT3 in tumor tissues, the more obvious the proliferation and metastasis of tumor cells." (PMID 30837865, 2019).
tumor (continued). "Activated STAT3 is known to regulate tumor cell metastasis and angiogenesis; additionally, diverse tumor types showed persistent activation of STAT3." (PMID 31783627, 2019). "In vitro, STAT3 silencing in UBC cell lines significantly reduced tumor cell viability and invasion." (PMID 31438567, 2019). "The role of STAT3 in promoting molecular programs in cancer cells that induce tumor metastasis and therapy resistance mechanisms continue to emerge, as does the impact of STAT3 as a suppressor of immune cell function in the TME." (PMID 31684144, 2019). "In particular, upon c-Src activation, STAT3 promotes tumor cell survival and proliferation by transactivating BCL2L1 (that encodes the Bcl-XL protein) and MCL1, two crucial anti-apoptotic genes that override cell death regulatory pathways." (PMID 31569642, 2019). "Phosphorylated STAT3 (p-STAT3) dimerizes spontaneously, migrates into cell nucleus and activates the expression of downstream genes to regulate the tumor cell growth, proliferation, differentiation and metastasis." (PMID 31375715, 2019). "STAT3 knockdown resulted in the reduction of OSCC tumorigenesis/stemness (decrease in the OSCC tumor sphere formation) and oncogenic exosomal cargo contents such as β-catenin, TGFβ1 and miR-21-5p." (PMID 31878245, 2019). "STAT3-activating cytokines such as IL-6 and IL-10 are found in abundance within the tumor microenvironment." (PMID 31766350, 2019). "Our data underline the potency of AF1q to enforce and link the two major oncogenic pathways WNT and STAT3 involved in tumor initiation, progression, and dissemination." (PMID 31671695, 2019). "Being involved in numerous signalling pathways and over-expressed in tumour cells compared to normal tissues, Stat3 is considered to be a potential target for future antitumor therapies." (PMID 31690341, 2019). "Previous studies have shown that silencing of FAK expression inhibited migration and EMT in tumor cells, and the STAT3 and NF-κB signaling pathways have been shown to play an important role in the metastasis of GC and EMT." (PMID 31019895, 2019). "Data showed that PAD-feeding increased tumor growth compared to the matched CD-feeding, which was reversed by STAT3 inhibition." (PMID 31474764, 2019). "In short, high expression of lincRNA-p21 increases its binding to STAT3, inhibiting STAT3 transcriptional activity and suppressing tumor progression and vice versa." (PMID 30857539, 2019). "It is also known that IL-6 can activate the STAT3 pathway in the tumor microenvironment, induce a large number of inflammatory genes and further promote angiogenesis to alter the proliferation of tumor cells." (PMID 31417646, 2019). "In a previous study, we demonstrated that cancer prostatic tissues from different oncological patients exhibited a specific STAT3 post-translational modification pattern depending on the tumor stage." (PMID 31500219, 2019). "STAT3 activation can promote increased expression of the anti-apoptotic protein Bcl-xL, which permits the survival and continued growth of tumor cells." (PMID 31528182, 2019). "We also noticed that SG-1721 was effective in reducing the expression of various proteins, including p-STAT3 in tumor tissues." (PMID 31058868, 2019). "Since its pivotal roles in inflammation-related diseases and neoplasm have been highlighted, the rationale for developing small molecules targeting the STAT3 signaling pathway is solid." (PMID 32257917, 2019). "STAT3 phosphorylation was corroborated by immunohistochemical stainings in primary tumor biopsies, showing higher levels of STAT3 phosphorylation at residues S727 and Y705 compared with adjacent non-tumor tissue or peripheral nerve tissue." (PMID 30645971, 2019). "Intriguingly, STAT-3 signaling was found to be key in driving the transformation of tumor progenitors and HCC progression in animal models." (PMID 31456946, 2019).
tumor (continued). "A similar story occurs for STAT3, so that various research studies have confirmed that the STAT3 signaling pathway incredibly increases tumor migration, tumor size and tumor malignancy." (PMID 31569687, 2019). "For example, environmental-STAT3 plays dominant roles in establishing or maintaining an immunosuppressive TME and is associated with tumor intrinsic and extrinsic factors, such as immune infiltration and copy number variation (CNV) burden." (PMID 31796877, 2019). "A crucial role of STAT3 in tumor onset and progression, tumor cell invasion, metastasis and angiogenesis has been largely demonstrated." (PMID 31456939, 2019). "Curcumin has been shown to inhibit STAT expression, specifically regarding the activity of STAT3, and most of the studies performed to investigate the effect of diarylpentanoids on tumours focus on STAT3 over STAT1 and STAT2." (PMID 31295798, 2019). "Several in vitro and in vivo studies have demonstrated that the inhibition of STAT3 leads to tumor growth inhibition." (PMID 30691132, 2019). "Immunohistochemistry was conducted to identify protein expression of S1PR1 and p- STAT3 in tumor tissues." (PMID 31438989, 2019). "It has been found that CD5+ Bregs inhibit tumor immune response by activating STAT3, thus promoting tumor development." (PMID 31662750, 2019). "Tumor-induced inflammation involving the IL-6/gp130/STAT3 and ERK5/STAT3 axes was shown to drive a pro-tumor transcriptomic program." (PMID 31766350, 2019). "We found the expression of TSLP/TSLPR and STAT3/p-STAT3 in tumor tissues treated with the anti-TSLP antibody was significantly decreased compared with the vehicle group." (PMID 31885639, 2019). "Increased expression of TNFα results in a prolonged and sustained activation of NF-κB and STAT3 signaling thus activating several tumor cell resistance mechanisms in GSCs." (PMID 30854231, 2019). "IL‐6 levels secreted in media and IL‐6 mRNA levels in tumor tissues, and expression of p‐STAT3 is upregulated in cells with overexpression of LNRRIL6 and is downregulated in LNRRIL6 knockdown cells." (PMID 31246342, 2019). "STAT3 activation results in several pro-tumorigenic outcomes such as proliferation, inhibition of apoptosis, epithelial-mesenchymal transition (EMT), tumour angiogenesis, and tumour-associated inflammation." (PMID 30679726, 2019). "It has a direct growth stimulatory effect on many tumour cells by activating several signalling pathways including Ras/Erk and STAT-3." (PMID 31010082, 2019). "TGF-β is another cytokine secreted by inflammatory or tumor cells that can increase PD-L1 expression in DC in a STAT3-dependent manner." (PMID 31480382, 2019). "RNAi-mediated genetic deletion of Lpar6 impaired HCC tumor growth in tumor xenograft assays, probably through a Signal-transducer-and-activator-of-transcription-3 (STAT3)/proto-oncogene pim-3-dependent mechanism." (PMID 31652837, 2019). "The activation of STAT3 is indispensable in the process of tube formation, and blocking the activity of STAT3 can inhibit the migration and microvascular production of tumor vascular endothelial cells." (PMID 31885639, 2019). "Starved tumor cells activate NF-κB and STAT3 via endoplasmic reticulum (ER) stress and secrete cytokines that stimulate tumor survival and clonogenic capacity." (PMID 31557897, 2019). "Additional translational studies on patients treated with STAT3 inhibitors are awaited to understand their effects on the complexity of tumor biology." (PMID 31480382, 2019). "In cancer cells, constitutive activation of STAT3 breaks the strict control mechanism of downstream gene transcription and involves in tumor growth, survival, invasion, metastasis, and angiogenesis." (PMID 31534119, 2019). "STAT3 plays a crucial role in signaling pathways that promote cellular proliferation, tumor angiogenesis, invasion, and migration." (PMID 31456939, 2019).
tumor (continued). "Still, inhibition of PI3k or Stat3 triggers apoptosis of tumor cells specifically due to their high E2F levels, rather than merely growth retardation." (PMID 30717267, 2019). "They identify IL-11 as a key factor that increases after surgery and show that blocking of STAT3 signaling induced by IL-11 reduces proliferation of the tumor cells and, eventually, HCC." (PMID 31683891, 2019). "Inhibition of the STAT3 feed-forward activation diminished tumor growth and metastasis and resensitized cells to therapy." (PMID 31684144, 2019). "Further, the phosphorylation status of STAT3 found in resected tumor sections correlated with the results obtained in the cell lines and showed markedly reduced levels of p-STAT3 in EF24-treated tumor tissues." (PMID 30949204, 2019). "The IL-6/JAK/STAT3 pathway contributes to treatment resistance promoting tumor cell survival after targeted anticancer drugs or ADT." (PMID 31143708, 2019). "Myeloid development into DCs is impaired by STAT3 signaling, and inhibition of JAK2/STAT3 has been shown to enhance anti-tumor responses through the promotion of DC maturation in preclinical models." (PMID 31921140, 2019). "BMA secrete abundant IL-6, which induces the epithelial-mesenchymal transition in tumour cells via the JAK2/STAT3 pathway, and strengthens the metastatic potential of tumour cells via PI3K/AKT." (PMID 31334678, 2019). "As it was shown in numerous studies PI3K/Akt, Ras/MAPK, and STAT3 pathways are commonly activated in tumor cells." (PMID 31681332, 2019). "Capsaicin treatment blocks the activation of activator protein 1 (AP-1), nuclear factor kappa B (NF-κB), and signal transducer and activator of transcription 3 (STAT3) signaling pathways that are activated and responsible for tumor growth." (PMID 31600949, 2019). "Some reports have shown that STAT3 activation promotes tumor cell survival under stress condition and is an attractive target in multiple cancers." (PMID 31777595, 2019). "Since STAT3 KO inhibits spheroid formation capability, we investigated its effect on tumor growth in xenograft models in either NOG or athymic nude mice." (PMID 31534498, 2019). "The results of the current work clearly showed that PH exhibited anticancer potential in vitro and retarded tumor growth via targeting the SHP-1/STAT3 and AKT/VEGFR2 signaling pathway." (PMID 31619257, 2019). "STAT3 plays a vital role in transcriptional regulation of genes involved in cell proliferation and tumor progression triggered by cytokines and growth factors such as EGFR and FGFR." (PMID 31485222, 2019). "Secreted HMGB-1 activates TLR9, which encourages tumor progression via activation of related intracellular growth signaling pathways, involving phosphorylation of p38, Stat3, JNK and p65 of NF-kB." (PMID 31474975, 2019). "Further characterization of these animals showed that there was higher expression of phospho-STAT3 in the splenocytes of tumor bearing mice compared to naïve, independently of the SW treatment." (PMID 30840689, 2019). "In fact, IL6/JAK/STAT3 signaling is expected to drive proliferation, survival, and invasiveness of tumor cells, and to suppress the anti-tumor immune response." (PMID 31357501, 2019). "Subsequent targeting of STAT3 in myeloid cells disrupted metastatic tumor outgrowth, suggesting STAT3 plays an integral role in priming distant metastatic sites for tumor cell outgrowth." (PMID 31684144, 2019). "Together, these studies indicate that flubendazole is a promising anticancer agent which effectively inhibits tumor growth by inhibiting the STAT3 signaling pathway and activating autophagy." (PMID 31287013, 2019). "We also found abolished expression of the suppressor of cytokine signaling 1 (SOCS1) in DFTD tumor cells, a known inhibitor of STAT3 activation." (PMID 30645971, 2019).